GLI2 (GLI family zinc finger 2)
Diseases named in the same sentence as GLI2 in open-access papers (continued):
Sharing a sentence is not in itself a finding about the gene and the disease.
tumor (continued). "Additionally, we found that GLI2 expression significantly correlates with the level of tumor-infiltrating CAFs, second to TGFβ3, providing further support for targeting this signaling axis as a therapeutic target." (PMID 40027190, 2025). "Thus, employing multiple approaches, we confirmed a positive correlation between fibrosis and GLI2, presenting the fibroblast compartment in the tumor stroma as the major source of GLI2 activity." (PMID 40449600, 2025). "We also examined the TGFβ3/GLI2/YAP1 (the TGY signature) expressions in the tumor samples." (PMID 40027190, 2025). "Our study found that SH downregulated the protein and mRNA expression of SHh, PTC, SMO, Gli1, and Gli2 in the Hedgehog pathway, suggesting that SH might inhibit tumor progression via suppressing the Hedgehog pathway activation." (PMID 41444284, 2025). "To investigate whether the GLI2/DEC1 axis is essential for tumor formation in vivo, we isolated tumors from mice." (PMID 40133270, 2025). "Of note, we observed higher nuclear GLI2 expression in OSCC tumor lesions with high collagen fiber accumulation with the AUROC value of 0.6 (p < 0.01), indicating a positive correlation between nuclear GLI2 positivity and collagen accumulation (indirectly reflecting tumor stiffness)." (PMID 38976559, 2024). "This means that the non-canonical GLI-2 activation increased the tumor aggressiveness and the risk of HCC recurrence." (PMID 38730691, 2024). "Finally, we sought to elucidate the clinical relevance of stromal remodeling that increases tumor stiffness and its role in promoting tumor progression through the mechanical activation of GLI2." (PMID 38976559, 2024). "While studies investigating the role of GLI family genes in cancer have primarily focused on GLI1, the contribution of GLI2/3 to tumorigenesis, especially in the context of the tumor immune microenvironment (TIME), remains largely unknown." (PMID 38498906, 2024). "The trend seen in all samples is again seen here in the sinonasal adenocarcinoma subgroup, with PTCH1 expression significantly different between the healthy epithelium and healthy stroma (p < 0.0001), and GLI2 expression significantly different between the tumor and tumor stroma (p = 0.030)." (PMID 38731849, 2024). "The results indicated a decrease in tumor size, growth rate, GLI2 messenger RNA, and protein expression, indicating that GLI2ASO may serve as a specific treatment for BLCA with promise for advancement." (PMID 39659999, 2024). "Moreover, Spearman correlation analyses conducted on tumor tissues obtained from TCGA demonstrated significant positive correlations between GLI1 and GLI2 in 30 tumor tissues, with only one tissue showing a significant negative correlation." (PMID 38498906, 2024). "Similarly, ciliary ablation in basal cell carcinoma (BCC)‐like tumours, induced by an activated form of SMO, inhibited the growth of carcinoma, conversely, in tumours induced by activated GLI2, carcinogenesis was accelerated." (PMID 39234399, 2024). "Additionally, an inverse relationship between Gli2 and HLA class I antigens has been previously established in other tumor models during acquired drug resistance of tumor cells compared to wild type." (PMID 37444470, 2023). "It is suggested that growth factors, including SHH, produced by tumor cells paracrinely induce Gli1 and Gli2 expressions in tumor vascular endothelial cells, and various angiocline factors produced by tumor vascular endothelial cells induce SHH and Gli1 in tumor cells." (PMID 37240209, 2023). "However, this study doesn’t uncover the mechanisms of how tumor-derived GLI2/TGF-beta axis regulates NK cell activity." (PMID 38159250, 2023). "Finally, SPOP and Gli2 can substitute HIB and Ci to mediate the same tumor-like eye phenotype in Drosophila, in mammalian cells, hRpb7 stability is similarly regulated by Gli2 and SPOP, indicating that they are functionally conserved." (PMID 37554435, 2023).
tumor (continued). "It is thought that cilia deletion could activate SMO to inhibit tumor growth, while promoting carcinogenesis was induced by activated Gli2." (PMID 37737843, 2023). "In addition, single-cell RNA sequencing on DDLPS tumors should be performed to determine if Gli2 and Hedgehog signaling are expressed in tumor cells or in other mesenchymal populations, such as fibroblasts or progenitor cells, within the tumor mass." (PMID 37444470, 2023). "Likewise, Chakrabarti and colleagues showed that GANT61 treatment reduces PDL1 expression and tumor cell proliferation in gastric cancer organoids derived from GLI2-expressing mice." (PMID 36674836, 2023). "Besides, we find down-regulation of tumor-derived GLI2 decreases the expression of tumor-derived PDL1 and IL6, and it also leads down-regulation of NK cell-derived PD1 and TIM-3, all of which are restored by adding TGF-beta active protein." (PMID 38159250, 2023). "High Gli2 expression is related to decreased E-cadherin’s expression and enhanced tumor cell invasion which may accelerate TGF-β-induced EMT and tumor growth." (PMID 37205317, 2023). "Because GLI1 and GLI2 facilitate the propagation of cells with damaged DNA, their expression may be naturally higher in cells that form the earliest precursor tumor lesions." (PMID 35505292, 2022). "We were surprised to find that total myeloid cells and macrophages do not change following the loss of Gli2/Gli3 in our tumor implantation experiments, in contrast to our KF;Gli2/Gli3 cKO model." (PMID 35867772, 2022). "Noncanonical activation of GLI1 and GLI2 often occurs through crosstalk with other pathways driven by oncogenic drivers or loss of tumor suppressors." (PMID 36010600, 2022). "We next wanted to determine why Gli2/Gli3 KO fibroblasts fail to promote tumor growth." (PMID 35867772, 2022). "Furthermore, it was found that GLI2 ablation suppressed the tumor weight in si-GLI2-1 group compared with the control group." (PMID 35382824, 2022). "Non-canonical upregulation of GLI2 causes tumor cells to adopt a more basal subtype, leading to an increase in mesenchymal markers and a decrease in epithelial markers." (PMID 35867772, 2022). "However, a novel PTCH1::GLI2 gene fusion was found in the tumor cells, instead of the previous reported characteristic MALAT1-GLI1 gene fusion or recent described EWSR1-CTBP1 fusion in gastroblastomas." (PMID 36147912, 2022). "Moreover, DDP treatment alone showed a limited ability to inhibit tumor growth in cells expressing normal levels of Gli2 as compared with the control group because of DDP resistance." (PMID 35059317, 2021). "In contrast, these key Hh pathway components were found to be significantly over-expressed in VSCC compared to normal vulval epithelium: SHH (median 1.0), PTCH1 (median 2.0), GLI1 (median 3.5) and GLI2 (median 3.5), and their expression were uniformly distributed across the tumour." (PMID 34480080, 2021). "Taken together, these findings validated that miR-636 inhibited the EMT and growth of OVC tumor in mice by silencing Gli2, and injection of agomiR-636 could effectively suppress tumor growth in the xenograft models." (PMID 33472614, 2021). "To evaluate the expression patterns of genes involved in tumor-induced osteolysis with respect to α2β1 integrin, we performed qPCR and western blot analysis for PTHrP and Gli2 and TGFβrII and RUNX2 in MDA-Ctrl or MDA-OEα2 cells, and MDA-Parental or MDA-Bone cells." (PMID 34199096, 2021). "These metastatic cells undergo rapid proliferation and differentiation typical of tumor heterogeneity and become locally invasive through basement tissues and manifest as tumor islands in the gastric mucosa—features only present with activated GLI2." (PMID 33494284, 2021). "Furthermore, the decrease in α2β1 integrin expression correlated with an increase in the genes PTHLH and the hedgehog transcription factor Gli2, which are involved in tumor-induced osteolysis." (PMID 34199096, 2021).
tumor (continued). "Moreover, we demonstrated that Gli2 knockdown can reverse the DDP resistance of OC cells in nude mice transplanted with tumor cells." (PMID 35059317, 2021). "Taken together, these findings elucidated that the Smo-Gli2-miR-636 axis in OVC may lower tumor growth by suppressing EMT." (PMID 33472614, 2021). "Furthermore, a high level and increased activity of Gli2 in the epidermis is sufficient to promote the formation of basal cell carcinoma and maintain tumor growth." (PMID 31901237, 2020). "Pan-cancer analysis of the correlation of GLI1 and GLI2 with 19,540 genes expressed in 30 tumor types revealed that GLI1 and GLI2 are mutually the most correlated genes, and that all HH and TGFB genes are in the top 20 percentiles of most correlated genes with GLI1 and GLI2, with one exception." (PMID 32879407, 2020). "Furthermore, in comparison with peri-tumor tissues, a distinctly decreased expression of miR-15a-5p and miR-15b-5p, and an obviously elevated expression of GLI2 in HCC tissues were observed." (PMID 32398664, 2020). "We found that GLI2 knockdown significantly reduced the size of tumor spheres." (PMID 30382189, 2019). "It has been reported that GLI1 and GLI2 play important roles in tumor development and progression." (PMID 31783569, 2019). "Interestingly, such a mutation correlated with the splicing-dependent inactivation of the PTCH1 tumor-suppressor gene and activation of the GLI2 and CCND2 oncogenes in SHH-MB, supporting the biological relevance of U1 snRNA mutation in this tumor." (PMID 31861467, 2019). "Importantly, GLI2 is required for maintaining the basal-like state as GLI2 knockdown in tumor derived human and mouse PDA cell lines suppresses the basal-like program in vitro, attenuating expression of mesenchymal and stem cell markers." (PMID 31134896, 2019). "Importantly, silencing of GLI2 in these tumor lines has been shown to partially restore sensitivity to the inhibitory effects of sonidegib." (PMID 30558232, 2018). "We also observed a positive correlation between high GLI2 expression in the tumor and a higher GS score, indicating that this might be a marker for an aggressive tumor phenotype." (PMID 28877722, 2017). "Higher epithelial GLI2 expression in the tumor was found to correlate with higher pathological GS (p = 0.047), indicating that this might be a potential marker for aggressiveness in this PCa cohort." (PMID 28877722, 2017). "GLI2 is a pro-invasive protein present in most tumor cell lines and this protein could substantially contribute to the stably elevated survivin levels observed in tumors." (PMID 26775700, 2016). "After knock‐down of Gli2, the toxicity of Gli2 to tumor cells was largely attenuated, indicating that the inhibition of tumor growth by iG2 could be attributed to the inhibition of Gli2 activity." (PMID 27465044, 2016). "Gli-2 was expressed in the progenitor cells, and weakly expressed in tumor cells." (PMID 27007126, 2016). "Knockdown of either Gli2 or KIF20A significantly reduced tumor volume and weight." (PMID 27036048, 2016). "Moreover, increased GLI2 expression correlated with poor survival of OS patients, indicating that GLI2 also contributes to tumor progression." (PMID 25992885, 2015). "The GLI2 transcription factor is known to be that often overexpressed in cancers and contrib­ute to the progression of a variety of neoplasms by regulating the cell cycle progression and apoptosis; it is also known that GLI2 is directly induced by TGF-β and SMAD signaling." (PMID 25895132, 2015). "EMT is a process that exerts influence on many molecular, such as TGF-β, E-cadherin, N-cadherin Vimentin, ZEB-1, SMAD-2, SMAD-3, SMAD-7, GLI1 and GLI2; these molecules are closely associated with typical phenotype changes of EMT in tumor cell growth and metastasis." (PMID 25895132, 2015). "Although GIN is a hallmark of human cancer, we provide evidence, indicating that GLI2 may have a key role in driving such events in human neoplasms." (PMID 24481442, 2014).
tumor (continued). "Our current findings indicate for the first time that the expression level of Gli2 is high in HCC tissue, and this high expression shows a significant association with poor clinical outcome after hepatectomy and a more aggressive tumor phenotype because it induces EMT changes." (PMID 23356443, 2013). "Knockout of GLI2 in PCa cells suppressed tumor growth both in vitro and in vivo." (PMID 23880852, 2013). "The bifunctional nature of Ci, and of the mammalian homologues Gli2 and Gli3, could fulfil oncogenic or tumour suppressor roles in function of the status of the Hh signalling." (PMID 23667323, 2013). "The hyperactivation of the ERK and AKT pathways in tumor cells may provide an environment for GLI2-mediated transcription of the immunosuppressive TGF-β1." (PMID 22859956, 2012). "Furthermore, inhibition of tumor cell actomyosin contractility in both pharmacological and genetic models decreased Gli2 and PTHrP expression." (PMID 21085597, 2010). "Previous studies have suggested that human GLI2 mRNA may exist in at least four different isoforms, which can be detected in tumor cell lines or tissues." (PMID 16553965, 2006). "SMO mutations may sometimes prevent long-term therapeutic benefits from occurring; in other circumstances, mutations in downstream components of the SHH pathway (for instance, MYCN or GLI2 amplifications) or in other pathways might render tumor cells resistant to these medications." (PMID 38391759, 2024). "Furthermore, a greater histological grade of the tumour was associated with overexpression of GLI1, GLI2, PTCH1 and SMO, which may indicate a critical function for Hh signalling in HNSCC malignancy." (PMID 39234399, 2024). "Thus, we hypothesized that elevated Gli2 expression may indicate an immune-exclusive tumor environment." (PMID 37444470, 2023). "Co-amplification of Gli1 and Gli2 occurs frequently in malignancy, but dependence on Gli1 or Gli2 varies between cancers, between subtypes, and between cell lines of the same subtype; Hh may even be activated heterogenously within the tumor microenvironment." (PMID 37954979, 2023). "Thus, we collected co-expression data on bulk tumor RNA-seq collected for the TCGA-SARC cohort through CBioPortal to better understand transcriptional associations that Gli2 may display within DDLPS tumors." (PMID 37444470, 2023). "We next assessed whether Gli2/Gli3 KO fibroblasts impacted the growth of tumor cells directly." (PMID 35867772, 2022). "Some studies showed that Gli1 is linked to tumor resistance, whereas others suggested that Gli2, rather than Gli1, may be more predictive of resistance." (PMID 35059317, 2021). "Moreover, the ROC1 and SUFU expression levels were associated with the tumor pathological grade, whereas the ROC1 expression was inversely associated with the SUFU expression (P = 0.014) but positively associated with the Gli2 expression (P = 0.001)." (PMID 33499884, 2021). "Amplification of chromosomal regions containing GLI2 was also found in a model of vismodegib resistance, as well as in two of three sonidegib-resistant MB tumors, in which the increased expression of GLI2 mRNA has been shown to mediate tumor growth independently from SMO." (PMID 30558232, 2018). "In univariate analysis, the factors significantly associated with OS were tumor size, TNM stage, differentiation, tumor encapsulation, vascular invasion, and Gli2 expression, and those significantly associated with DFS were tumor size, tumor encapsulation, vascular invasion, and Gli2 expression." (PMID 23356443, 2013). "ASO-mediated knockdown of MIR31HG reduced tumor stemness and metastasis by recruiting the WDR5/MLL3/P300 complex to modulate the expression of GLI2." (PMID 41409273, 2025).
tumor (continued). "Our findings revealed that, with the exception of GLI2 and CSNK1E, the majority of these prognostic‐related HRGs exhibited elevated levels of methylation within tumor tissues." (PMID 41427028, 2025). "Previous research reported that IFN induced USP18 mRNA expression in tumor cells, and the Hedgehog (Hh) signaling pathway upregulated USP18 expression through Gli2-mediated transcriptional activation following spinal cord injury." (PMID 40514377, 2025). "Protein expression demonstrated upregulation of the Hh pathway in mBCC tumours including GLI1 and GLI2, whereas nodBCC had a normal level of expression of the Hh pathway, not above the levels of physiological activation." (PMID 41373535, 2025). "Immunoblot of tumor bulk protein and in situ immunohistochemistry indicated that MIR31HG ASO therapy downregulated expression of GLI2, ABCG2, and SOX2." (PMID 37950038, 2024). "Analysis of paired tumor and normal tissue samples from the TCGA database further verified significant expression of GLI1, GLI2, and GLI3 in nine, ten, and ten types of tumors, respectively." (PMID 38498906, 2024). "Regarding tumor tissues, TGCT, MESO, and SKCM exhibited the highest levels of GLI1, GLI2, and GLI3, respectively." (PMID 38498906, 2024). "Combining data from TCGA tumor samples and normal tissues from the GETx database showed significant expression of GLI1, GLI2, and GLI3 in 24, 28, and 23 types of cancer, respectively." (PMID 38498906, 2024). "Currently, there is limited information that allows us to understand the actual effect of GLI1 and GLI2 inhibition, although it has been demonstrated that GLI1/2 inhibitors can block tumor proliferation in mice with human tumor xenografts." (PMID 38275873, 2024). "In CCA, TAMs can promote tumor progression through various pathways, such as the SHH/GLI2/TGF-β1 pathway and the aPKCγ/CCL5 pathway, as previously summarized." (PMID 39290697, 2024). "Knockdown of SHARPIN in TE354.T cells, a human BCC cell line, enhanced tumor cell proliferation, possibly due to the increased phosphorylation of two transcriptional factors, c‐JUN and GLI family zinc finger 2 (GLI2)." (PMID 38017534, 2023). "An intraperitoneal administration of GANT61 (40 mg/kg), a small-molecule inhibitor of Gli1 and Gli2, resulted in significant inhibition of cortical bone destruction, TRAP-positive osteoclasts within the cortical bone, and endomucin-positive tumor vessels." (PMID 37240209, 2023). "Gli1 displays a genomic association with LPS tumor initiation; however, it is not the only transcriptional activator of the Hedgehog pathway and can often display both overlapping and distinct transcriptional targets with that of Gli2, the other primary Hedgehog transcriptional activator." (PMID 37444470, 2023). "In transgenic mice overexpressing GLI2 driven by the keratin 5 (K5) promoter, CCND1 and CCND2 were significantly upregulated in BCC biopsies, promoting sustained tumor growth and expansion of BCC." (PMID 34572373, 2021). "In 33 tumor cell lines, SMO gene expression was highest among all Hh members, and its expression was significantly and positively correlated with GLI2 transcript levels." (PMID 34572373, 2021). "In both tumour and normal vulval epithelium, expression of SHH ligand was localised to the cytosol; PTCH1 to the membrane, cytosol and nucleus; and GLI1, GLI2 and GLI3 to the cytosol and nucleus." (PMID 34480080, 2021). "Significant overexpression of both GLI1 and GLI2 was found in intrahepatic CCC, when compared with non-tumor tissues (p < 0.001 and 0.05, respectively), suggesting a possible tumorigenic effect of SHH signaling during the development of CCC." (PMID 34948011, 2021). "Conversely, inhibition of LRP5/6 (receptor of Wnt3a ligand) with sclerotin reduced basal GLI2 transcript levels in MDA-MB-231 cells, proving the existence of a paracrine Wnt signaling crosstalk between bone marrow stromal cells and tumor cells." (PMID 34572373, 2021).